MET (MET proto-oncogene, receptor tyrosine kinase)
Diseases named in the same sentence as MET in open-access papers (continued):
Sharing a sentence is not in itself a finding about the gene and the disease.
tumor (continued). "Increased mRNA and protein levels of the metalloproteases ADAM10 and ADAM17, responsible for MET ectodomain shedding, increase invasive behavior of OSCC and are accordingly associated with advanced tumor stages, regional lymph node metastasis, and reduced survival." (PMID 35326642, 2022). "Furthermore, amivantamab has the ability to induce trogocytosis and engage immune effector cells to eliminate EGFR and MET-presenting tumor cells through antibody-dependent cellular cytotoxicity." (PMID 35565287, 2022). "For example, a bidirectional activation of EGFR and MET in tumor cells has been reported." (PMID 35269415, 2022). "It has been reported that EGFR/MET may be involved in resistance of RTKs target therapy, and MET amplification is important in tumor metastasis." (PMID 35428350, 2022). "We could demonstrate that the majority of tumor lesions showed a visually and quantitatively increased uptake while primary renal tumors and bone metastases showed the highest c-MET uptake." (PMID 34708249, 2022). "Deletion of MET in neutrophils amplified the tumor growth and metastasis." (PMID 35081970, 2022). "High expression of MET and Snail correlate with highly invasive tumor phenotypes in breast cancer." (PMID 35301291, 2022). "Tumor resistance to FGFRis is identified in multiple tumor types and are mostly related to activation of different signaling pathways including MET, Eph3B, ERBB2/3 or EGFR and/or activation of intracellular signaling pathways without tyrosine kinase receptor dependence." (PMID 35444941, 2022). "Hepatocyte growth factor (HGF) contribute to tumor development through its specific receptor MET." (PMID 35127296, 2022). "Interestingly, we found the presence of CTM in mice with widespread lung metastasis, and the expression level of EGFR/MET was higher than that in primary tumor and lung metastasis." (PMID 35428350, 2022). "MEG3 directly targets the proto-oncogene c-MET (hepatocyte growth factor receptor) to block cell proliferation and delay cell cycle progression, and it also displays an anti-tumor effect through manipulating the p38/ERK/Akt and Wnt/β-catenin pathway in a MEG3/miR183/BRI3 dependent manner." (PMID 36248960, 2022). "Although the primary targets of BMS794833 are MET and VEGFR239, BMS794833 also inhibits the polarization of monocytes into tumor-associated macrophages through a polypharmacological effect rather than inhibition of MET and VEGFR240." (PMID 36056187, 2022). "Successfully inhibited tumor growth using EGFR-MET bispecific antibody in drug resistant PDX model supported our theory regarding the role of EGFR activation in the resistance to MET-targeted TKIs." (PMID 36338758, 2022). "Among the five critical genes previously obtained from survival and molecular docking analysis, MMP9 & MET were the upregulated in tumor samples (COAD and READ), while PDGFRA (COAD and READ) & PTGS2/COX-2 (READ) were downregulated according to the expression analysis by box plots." (PMID 36110531, 2022). "c-MET expression was previously shown to impact neutrophil function in the tumor environment." (PMID 35041723, 2022). "c-MET can be activated by several abnormal factors and is involved in the occurrence and progression of different malignant tumors; thus, it is the “driving factor” of tumor occurrence." (PMID 35874635, 2022). "Indeed, mir-378 was reported to modulate the phenotype of RMS cells through IGF1R regulation, whereas miR-206 over-expression reduced tumor growth in vivo by inhibiting c-MET." (PMID 36430468, 2022). "Besides osimertinib, MET amplification has also been reported in tumor biopsies from patients with lung adenocarcinoma who developed resistance to rociletinib." (PMID 35463360, 2022).
tumor (continued). "Previous studies demonstrated that MACC1 can regulate the expression of the oncogene c-MET and promote epithelial-mesenchymal transformation, migration, proliferation, angiogenesis, and drug resistance in various tumor cells through the HGF/c-MET/MAPK and HGF/c-MET/AKT pathways." (PMID 35874635, 2022). "MET is an RTK activated by hepatocyte growth factor (HGF) and mediates several physiological processes, such as embryogenesis and tissue repair; aberrant activation of MET by genetic alterations plays an important role in the proliferation, invasion, and metastasis of tumor cells." (PMID 36224343, 2022). "In addition, the signaling pathways affected by MET alterations are essential to predicting the tumor phenotype, as it is a proliferative or invasive disease." (PMID 36430388, 2022). "The results of this experiment showed that MACC1 could activate the HGF and then stimulate the phosphorylation of c-MET, thus enhancing the invasion ability of tumor cells." (PMID 35874635, 2022). "Thus, studies suggest c-MET not only as an anti-tumor target but also a good target for immunotherapy." (PMID 35081970, 2022). "It targets multiple kinases involved in tumor progression, such as MET and VEGFR2." (PMID 36080304, 2022). "Next-generation sequencing (NGS) suggested MET gene amplification in the tumor." (PMID 36482562, 2022). "However, c-MET based immunotherapies has to be till explored in HNSCC to explore its treatment efficacy against HNSCC tumor growth." (PMID 35081970, 2022). "Furthermore, crizotinib has been used in vivo to show antitumor activity in mice having tumor xenografts that expressed MET or on the fusion proteins EML4-ALK or NPM-ALK." (PMID 35565287, 2022). "In addition, MET inhibition, by enhancing the formation of DNA double-strand breaks and possibly alleviating tumor hypoxia, has been found to sensitize CRC cells also to irradiation, further expanding the actionability of MET in CRCs." (PMID 35582524, 2022). "Moreover, HGF/c-MET signaling is also involved in the regulation of tumor microenvironment, immune infiltration, and immune response." (PMID 35558557, 2022). "Furthermore, FTO depletion in PC cells weakened their tumor-forming capabilities in nude mice; those tumors had increased apoptosis, decreased proliferation markers, and MET conversion." (PMID 36497402, 2022). "Interference function of EGFR/MET attenuated anoikis resistance of tumor cells." (PMID 35428350, 2022). "Notably, the MET inhibitor capmatinib has a pivotal function in restraining PD-L1 expression and stopping tumor progression." (PMID 35907881, 2022). "Since our studies revealed potential PDAC dependence of PD-1/MET oncogenic signaling, we sought to determine whether therapeutic targeting of this axis could block tumor growth." (PMID 35804822, 2022). "Some solid tumors rely on MET gene activity for tumor cell proliferation and survival." (PMID 36482562, 2022). "The intra-individual heterogeneity could also possibly be a sign of (incipient) tumor dedifferentiation with a lower c-MET uptake in some RCC cells." (PMID 34708249, 2022). "While numbers of mice in the pilot study of trametinib in combination with MET inhibitor glesatinib were low, this regimen showed promising increased magnitude and durability of response (average decrease of 91% tumor volume, i.e., 320 mm3 to 29 mm3), compared to trametinib alone." (PMID 35343367, 2022). "Our results are in line with previous findings of MET in LUAD tumor tissue and plasma." (PMID 36544145, 2022). "Consequently, the release of HGF/MET-dependent NO by neutrophils promotes cancer cell killing, abating metastasis formation, and corresponding primary tumor growth (in several cancer models)." (PMID 35664746, 2022).
tumor (continued). "Many studies could show that upregulation of phosphorylated c-MET is correlated with larger tumor diameter, greater proliferation index, and worse overall survival." (PMID 34708249, 2022). "In addition, IL4 induces expression of HGF, which creates an immunosuppressive environment for cytotoxic natural killer cells via c-MET signaling in tumor cells." (PMID 36077870, 2022). "There is ample evidence in the literature reviewed above to suggest that targeting the HGF/c-MET pathway could be an effective anti-cancer strategy across a range of tumor types." (PMID 36034555, 2022). "Furthermore, c-MET expression on neutrophils contributes to the killing of tumour cells in the tumour microenvironment." (PMID 35041723, 2022). "These combined biological responses following MET activation may facilitate PTC tumor invasiveness and nodal metastasis." (PMID 35389070, 2022). "Assuming that a MET–DDR interface underlies MET dependency, here we monitored 116 DDR- and RTK signalling-associated phosphosites in a panel of MET-positive, MET-responsive as well as non-responsive tumor models following targeted MET inhibition." (PMID 36494469, 2022). "Concerning the receptor tyrosine kinase (RTK) MET, although mutations are rare in HCC and they predominantly occur in paediatric HCC, it is activated in close to 50% of cases, participates in tumour-stroma crosstalk, and correlates with poor prognosis." (PMID 36433941, 2022). "However, MET proto-oncogenes do participate in the progression of various solid tumors and mediate the proliferation and metastasis of various tumor cells." (PMID 35710379, 2022). "Therefore, it should be taken into consideration that treating cancer patients with MET inhibitors can lead to defective chemotaxis of neutrophils, and tumor cells can escape from tumor killing." (PMID 35986321, 2022). "MET plays a well-defined role as a selectable oncogenic driver of tumor proliferation." (PMID 35241019, 2022). "Furthermore, the expression levels of RAC1, CDK2, RUVBL2, and MET were upregulated in the tumor group compared to the control group and showed a noticeably positive correlation with the expression level of RHOA." (PMID 35406376, 2022). "In addition, the expression of tumor drug resistance genes, EGFR, and MET were remarkably higher among the high-risk group than low-risk patients, positively related to risk score." (PMID 36497225, 2022). "Therefore, how MET expression affects neutrophil functions remains to be thoroughly explored in diverse tumor contexts." (PMID 36514901, 2022). "In the majority of cancers, including HNSCC, MET is transcriptionally activated by stimuli such as hypoxia, inflammatory cytokines, stromal HGF, and pro-angiogenic factors, often abundantly present in the reactive tumor-associated stroma." (PMID 35326642, 2022). "Baseline tumor expression of c-MET was evaluated by IHC for 19 patients (out of n = 27)." (PMID 36034555, 2022). "Although MET immunoreactivity has been associated with advanced disease stage, tumor recurrence, and poor prognosis, no clear relationship has been established with response to MET-targeted therapy." (PMID 35326642, 2022). "The unexpected result regarding worse survival in patients with high plasma exposure to osimertinib or erlotinib might be explained by the occurrence of tumor resistance to EGFR-TKIs through off-target mechanisms including amplification of MET and HER2." (PMID 36145591, 2022). "Mass-spectrometry-based approaches could identify such potential substrates and open new insights into MET signalling and, subsequently, tumor biology." (PMID 36293286, 2022). "To conclude, inhibiting the activation of PSCs or the expression of c-MET in tumor cells in combination with ferroptosis inducers may reduce the dose of ferroptosis inducers and achieve better therapeutic effects." (PMID 35693705, 2022).
tumor (continued). "Other studies have described that the potentiation of HGF/MET activation by ectopic expression of HGF leads to hepatic, renal, and gut abnormalities, whereas MET overexpression confers susceptibility to tumor development." (PMID 35269415, 2022). "Moreover, c-MET has emerged as a key target for modulating the c-MET/HGF axis for tumor therapy, showing promising therapeutic potential for c-MET-positive tumors." (PMID 36233320, 2022). "Besides, in some of these studies, MET gene amplification up-regulated PD-L1 expression, especially correlating with PD-L1 overexpression—considered as such for a tumor proportion score > 50%." (PMID 34504652, 2021). "There was increased c-MET expression observed in both inflammatory and tumor-induced lymphatic vessels, and HGF-c-MET interaction could indirectly upregulate the VEGF/VEGFR expression via activating NF-kB molecule." (PMID 35087755, 2021). "For instance, neutrophils upregulates c-MET expression in tumor-bearing conditions." (PMID 34830850, 2021). "Previous studies have demonstrated that abnormal activation of MET signaling pathway could promote neovascularization, lymphangiogenesis, proliferation and differentiation of tumor cells, malignant tumor invasion and metastasis." (PMID 34123778, 2021). "miR-34a-5p overexpression may have a potential therapeutic benefit in HNSCC via MET inhibition and restoration of anti-tumor immunity." (PMID 33596979, 2021). "PIVKA-II binds to the hepatocyte growth factor receptor, c-MET, leading to tumour growth, invasion and tumour metastases via the JAK-1/STAT3 and ERK 1/2 MAPK signalling pathways, whereas AFP is thought to be more a marker for hepatic progenitor cells or their subtypes." (PMID 34853657, 2021). "Therefore, we hope to integrate the HGF/c-MET pathway and level of immune regulation to achieve tumor diagnosis and prediction." (PMID 34261467, 2021). "To identify whether c-MET addiction of 4T1 tumor cells and their concomitant sensitivity to c-MET blockade could explain the reduction in cell proliferation upon OMO-1 treatment, we evaluated c-MET expression in 4T1 primary tumors." (PMID 33731699, 2021). "MET amplification in ctDNA may predict disease progression in patients with AGC in the same way as MET amplification in tumor tissues." (PMID 33959414, 2021). "To evaluate whether MET mediates tumour sensitivity to olaparib, we used siRNA to silence MET expression and examined the growth of DU145 and PC3 cells in the presence of olaparib." (PMID 34761497, 2021). "In addition to pharmacological inhibition, genetic silencing of MET has been shown to reverse chemoresistance in different tumour types." (PMID 33526881, 2021). "Phospho-MET analyses in these experiments were performed with an antibody specific to pY1235-MET rather than the pY1234/1235-MET antibody used in the analyses of lysed biopsy cores, and the phospho-MET signal was unambiguously traced to the tumor cells." (PMID 34180036, 2021). "The inhibition of VEGFR-2 prohibits angiogenesis and attenuates tumor growth, but cancers may bypass this effect through the activation of MET." (PMID 33679971, 2021). "Accordingly, we found that combined inhibition of MET and FGFR in a basal B PDX resulted in a decrease in sphere-forming and CD44+CD24−/low populations, indicative of a loss of TICs and reduction in overall tumour burden." (PMID 33772015, 2021). "In line with our hypothesis, the vascular bed was identified as a potential target for c-MET inhibition based on its detectable expression of c-MET in primary tumor sections." (PMID 33731699, 2021). "Possible reasons include that MET activation triggers tumor growth, angiogenesis or metastasis." (PMID 34261467, 2021). "The high efficiency of the combined inhibition of c-MET and ILEI function on the inhibition of invasion and tumor growth of cancer cells bearing MET and FAM3C amplifications found in this study justifies the relevance of this co-amplification on clinical outcomes." (PMID 33596971, 2021).
tumor (continued). "As GDNF is highly expressed in NSCLC, we could hypothesize in RET inhibitors resistant cancer cells harboring MET amplification, a cross-talking between tumor microenvironment and TK receptors." (PMID 33806299, 2021). "High expression of MET in cetuximab-progressed tumors may indicate an existence of MET-dependent tumor cell population." (PMID 34335943, 2021). "While interactions between c-MET and human epidermal growth factor receptor (HER) family members allow tumor progression and treatment resistance, and cooperative signaling between c-MET and HER2 might be a mechanism by which c-MET promotes cancer progression." (PMID 33596971, 2021). "In addition, MET-silenced OR cells showed a significantly reduced ability to form colonies, migrate and generate tumor spheres." (PMID 33621951, 2021). "By expressing HGF, PSCs act in a paracrine way on the tumor cells expressing MET." (PMID 34298732, 2021). "Overall, these results suggest that, although aberrations of BAP1, CDKN2A, and other tumor suppressor genes are the commonest genomic cancer-driving hits in MM, some rare cases of MM might also be driven by genomic dysregulation of MET signaling." (PMID 34884673, 2021). "The present study also suggests AP-1/GGA2 can support the expression of other RTKs, MET and ErbB4, which might have a significant impact on cancer growth in HCC, since MET is known to be overexpressed in this type of tumor." (PMID 34799560, 2021). "Furthermore, higher expression levels of ADAM9, EFNB2, MET, and TMOD3 were significantly associated with increased tumor infiltration of macrophages, DCs and/or B cells." (PMID 33648511, 2021). "It was shown that the secretion of lactate could protect cells from damage under hypoxia conditions, promote angiogenesis and cell growth, and also contribute to activate MET-dependent signal transduction pathways in tumor cells to promote drug resistance." (PMID 38650282, 2021). "The MET signaling pathway plays an important role in cell migration, apoptosis, proliferation and differentiation, which can promote tumor cells to form more aggressive cell phenotype to avoid immunity and enhance the ability of tumor cells to survive, infiltrate and invade." (PMID 34054930, 2021). "Indeed, tumor sections from the combination treatment showed the most reduction in the expression of Snail, MET and α-SMA as compared to other sections." (PMID 33621951, 2021). "c-MET activation might promote WNT signaling inducing stemness on tumor cells, by involving AKT-mediated GSK3β activation and leading to phosphorylation of LRP5/6 and stabilization of β-catenin." (PMID 33562604, 2021). "This analysis suggests that MET expression and downstream signaling may impact tumor progression in SCNPC." (PMID 33471819, 2021). "Immunofluorescence staining of FFPE tissue was performed to evaluate whether MET and phospho-MET signals derived from tumor or stroma." (PMID 34180036, 2021). "These arguments together with our data suggest an approach in which ESCC patients with a homogenous overexpression of MET, showing complete IHC positiveness in cancer cells and high MET expression in different regions of the tumor mass, would be more likely to respond to anti-MET drugs." (PMID 34037097, 2021). "However, the good agreement observed between MET mRNA levels by nCounter and MET IHC staining in tumor cells indicated that, in most samples, the contribution of noncancer components to the nCounter results was not significant." (PMID 33236532, 2021). "Development of savolitinib resistance through a MET mutation after an initial clinical response and subsequent sensitivity of the tumor to a structurally distinct MET TKI strongly suggest that the tumor retained dependence on MET signaling throughout the course of patient therapy." (PMID 34516823, 2021).